IGF1R (insulin like growth factor 1 receptor)
Diseases named in the same sentence as IGF1R in open-access papers (continued):
Sharing a sentence is not in itself a finding about the gene and the disease.
pancreatic cancer (continued). "Investigators from MD Anderson Cancer Center presented data on genetic variations in the IGF1R pathway and prognosis in locally advanced pancreatic cancer." (PMID 20331897, 2010). "The PI3K/Akt/mTOR pathway is activated in pancreatic cancer by overexpression or activation of EGFR and insulin-like growth factor (IgF1R), by PTEN loss or secondary to k-ras mutation and activation of the Ras/Raf/MEK pathway." (PMID 20630061, 2010). "Also, IGF-1R has been recognized as a direct target of miR-497, which is detected in low levels in pancreatic cancer cells, while miR-497 inhibits cell proliferation and downregulates IGF-1R by targeting the 3′-UTR." (PMID 41153350, 2025). "Additionally, gemcitabine dose-dependent activation of IGF1R drives gemcitabine resistance in pancreatic cancer cells by inducing EMT-mediated phenotype switching." (PMID 39000545, 2024). "In a phase II clinical trial of advanced pancreatic cancer patients treated with IGF1R-directed monoclonal antibody MK-0646 combined with gemcitabine, high expression of IGF1 in the combined treatment group was found to be associated with reduced risk of disease progression or death." (PMID 39394189, 2024). "Furthermore, through the IGF-1/IGF-1R signaling pathway, p32 mediates pancreatic cancer's hepatic metastasis." (PMID 38169635, 2024). "In pancreatic cancer, IGF-1R activates RON to promote cancer metastasis." (PMID 38342894, 2024). "In addition, in vivo experiments found that PGG cured cancer cachexia by inhibiting IR and IGF1R in pancreatic cancer cells, thereby reducing glycolytic enzymes, hepatic gluconeogenesis, skeletal muscle protein hydrolysis, and fat lipolysis in tumor grafts." (PMID 37050924, 2023). "Furthermore, there are phase III trials for IGF1R antagonists/inhibitors, including ganitumab, in other cancers (e.g., non-small-cell lung cancer, pancreatic cancer, and Ewing sarcoma)." (PMID 37237509, 2023). "However, in clinical trials, the combination of gemcitabine with IGF-1R inhibitor received little overall survival benefits in advanced pancreatic cancer patients." (PMID 35252207, 2022). "Moreover, the dual inhibition of EGFR/HER2 and IGF-1R signaling did produce stronger antitumor effects than either monotherapies in pancreatic cancer, ovarian cancer, colon cancer, etc.." (PMID 36142299, 2022). "IGF-1R upregulation in pancreatic cancer cells contributes to cancer progression and metastasis." (PMID 34540690, 2021). "For example, CAFs produce an abundance of insulin-like growth factor 2 (IGF2) that renders cholangiocarcinoma and pancreatic cancer cells resistant to EGFR tyrosine kinase inhibitors (TKI) by activating the insulin receptor (IR)/insulin-like growth factor 1 receptor (IGF1R) signaling axis." (PMID 31067787, 2019). "This necessitates a better understanding of the role of IGF-1R signaling in pancreatic cancer." (PMID 29976975, 2018). "The present study is a major advance over previous studies on binding of IDG-1R fluorescent antibodies to pancreatic cancer as our model is orthotopic and therefore clinically relevant, including the fact that an endoscope-like device can detect the fluorescent IGF-1R antibody bound to tumor tissue." (PMID 26919100, 2016). "The goal of the present study was to determine whether insulin-like growth factor-1 receptor (IGF-1R) antibodies, conjugated with bright fluorophores, could enable visualization of pancreatic cancer in orthotopic nude mouse models." (PMID 26919100, 2016). "For example, miR-630 has been reported to regulate cisplatin-induced cell death in both non-small cell lung cancer as well as head and neck cancer, moreover, by targeting IGF-1R, miR-630 could induce apoptosis of pancreatic cancer cells." (PMID 26595523, 2016).
pancreatic cancer (continued). "Targeting IGF1R signaling may represent a promising therapy against the progression of pancreatic carcinoma." (PMID 27487118, 2016). "Thus, we examined the interactions between EP2/EP4- and IGF-1R-mediated cellular signaling in human pancreatic cancer cells." (PMID 25638159, 2015). "In addition, EGCG has anticancer effect in human pancreatic carcinoma cells by inhibition of both focal adhesion kinase and insulin-like growth factor-I receptor induction of CDK inhibitors, and inhibition of FAK and insulin-like growth factor-1 receptor." (PMID 26225138, 2015). "To conclude, our results demonstrate the significance of IGF-1R in pancreatic cancer." (PMID 24809702, 2014). "Plasma IGF-1R might also be used in differentiating pancreatic cancer from other pancreatic tumors (AUC = 0.634, 95%CI: 0.504–0.763, P = 0.057)." (PMID 24667580, 2014). "These molecular alterations in response to IGF-1R knockdown could contribute significantly to the inhibition of EMT in pancreatic cancer cells." (PMID 24809702, 2014). "Recent study proved that upregulation of miR-630 in pancreatic cancer cells could induce apoptosis by targeting IGF-1R." (PMID 24621930, 2014). "Therefore, based on mounting evidence for the efficacy of targeting IGF-1R in a broad spectrum of cancers, we have determined the effects of targeting IGF-1R in pancreatic cancer in this study." (PMID 24809702, 2014). "Furthermore, the over expression of miR-630 has recently been implicated in degradation of Insulin Growth Factor Receptor 1 (IGF1R) mRNA and protein levels and subsequent enhanced apoptosis in pancreatic cancer cells." (PMID 24655723, 2014). "The ultimate goal of this study is to identify whether IGF-1R signaling is an effective therapeutic target for pancreatic cancer with the potential to translate rapidly into clinical use." (PMID 24809702, 2014). "Therefore, our specific aim in our future work is to identify a molecular target that would be more specific for pancreatic cancer cells compared to normal cells which would still effectively target most of the protumorigenic functions of IGF-1R in PDAC." (PMID 24809702, 2014). "The value of plasma IGF-1R at diagnosis of pancreatic cancer was evaluated in the current study." (PMID 24667580, 2014). "Over-expression of IGF-1R has been found in a variety of malignancies including pancreatic cancer." (PMID 23675407, 2013). "IGF1R signaling might be associated with tumor aggressiveness, and IGFBP3 might show antiproliferative effects in pancreatic cancer." (PMID 23962053, 2013). "Decreased IGFBP3 production and increased IGF1R expression in pancreas tumors might enhance the tumorigenesis and cell motility as previously reported." (PMID 23962053, 2013). "The importance of IGF-1R in the proliferation of the pancreatic cancer cells, as well as their resistance to apoptosis, was documented by the observation that IGF-1R knockdown inhibited proliferation, enhanced 3-Cl-AHPC-mediated apoptosis, and inhibited sphere formation in PANC-1 cells." (PMID 22570653, 2012). "The expression of a number of proteins has been shown to be associated with poor survival of patients with pancreatic cancer, including expression of epidermal growth factor receptor (EGFR), insulin-like growth factor-1 receptor (IGF-1R), heat shock protein-27 (HSP27) and VEGF." (PMID 23140395, 2012). "Increased expression of IGF-1 and IGF1R in PDAC is closely associated with unfavorable clinical outcomes, with elevated levels correlating with poor survival rates and higher tumor grades, establishing them as prognostic indicators for pancreatic cancer patients." (PMID 39087024, 2024). "Moreover, C1QB levels in pancreatic cancer may serve as a predictor of disease given its role in the regulation of IGF-1/IGF-1R signaling, which plays a role in the cell spreading, and in the induction of hepatic metastasis." (PMID 37628784, 2023).
pancreatic cancer (continued). "Therefore, IGF-1R activation may support macropinocytosis-dependent growth of pancreatic cancer cells through the activation of the RAS/RAF/MAPK pathway." (PMID 36144235, 2022). "Plasma IGF-1R could be a new biomarker for guiding TNM stage of pancreatic cancer." (PMID 24667580, 2014). "Therefore, we speculated that miR-497 attenuated the malignancy of pancreatic cancer by partly suppressing IGF-1R/AKT pathway." (PMID 24667580, 2014). "The clinical values of plasma IGF-1R in pancreatic cancer are unknown." (PMID 24667580, 2014). "IGF-1R could be also a new plasma biomarker for guiding TNM stage of pancreatic cancer." (PMID 24667580, 2014). "In pancreatic cancer cell lines (PANC‐1 and HPAC) and human pancreatic adenocarcinoma tissues, the IGF‐1R was discovered to be abnormally over expressed." (PMID 39434498, 2025). "In pancreatic cancer cell lines such as PANC-1 and HPAC, downregulation of IGF-1R not only impairs proliferative and metastatic signaling through the MAPK and JAK/STAT pathways but also reduces EMT and insulin receptor β expression." (PMID 40918466, 2025). "In pancreatic cancer, the PDZ domain of GIPC1 can stabilize IGF-1R proteins and contribute to cell proliferation." (PMID 38186571, 2023). "In pancreatic cancer, BMS-754807, a small-molecule inhibitor of the insulin-like growth factor-1 receptor/insulin receptor, improves gemcitabine responsiveness." (PMID 37284310, 2023). "Another study showed that concurrent blockade of IGF1R and its EGFR/Her-2 simultaneously inhibited the pancreatic tumor growth and the stimulation of IRS-1, Akt, and MAPK phosphorylation." (PMID 36556296, 2022). "IGF-1R and FOXC1 regulate each other in pancreatic cancer and FOXC1 is a direct downstream signaling molecule of IGF-1/IGF-1R axis." (PMID 34540690, 2021). "On another hand, metformin disrupts interaction between insulin/IGF-1R and G-protein-coupled receptor (GPCR) signaling pathways that have a critical role in the development of pancreatic cancer." (PMID 33849540, 2021). "PGG were reported to antagonize insulin receptor/insulin-like growth factor-1 receptor (IR/IGF1R), hence sabotaging pancreatic cancer cells and ameliorating cancer cachexia." (PMID 33316951, 2020). "Given that BMS-754807 exhibits a potent antiproliferative effects on glioblastoma, colon and pancreatic carcinoma cellular models analyzed in this work, we believe that this compound could be useful for the treatment of different types of tumors independently of their IGF-1R activation status." (PMID 33322337, 2020). "We have determined the effects of the IGF-1R tyrosine kinase inhibitors BMS-754807 (BMS) and OSI-906 (OSI) on cell proliferation and cell-cycle phase distribution in human colon, pancreatic carcinoma, and glioblastoma cell lines and primary cultures." (PMID 33322337, 2020). "We have tested the effects of IGF-1R tyrosine kinase inhibitors BMS-754807 (BMS) and OSI-906 (OSI) on human colon, pancreatic carcinoma cell, and glioblastoma cell lines and primary cultures." (PMID 33322337, 2020). "On the other hand, overexpression of FOXC1 maintained the expression levels of IGF-1R even in the presence of PPP, indicating the positive feedback regulation between IGF-1R and FOXC1, which enhances pancreatic cancer growth." (PMID 29976975, 2018). "The synergy between IGF1-R inhibitor and ONC212 and the attenuation of BIP expression makes this combination a promising treatment for pancreatic cancer patients." (PMID 29137221, 2017). "Since ONC212 showed notable pre-clinical efficacy against pancreatic cancer, both as a single agent as well as in combination with an IGF1-R inhibitor, we wanted to test its potential in combination with FDA-approved drugs for pancreatic cancer." (PMID 29137221, 2017). "IGF-1R is the major receptor for IGF-I and IGF-II, and importantly expressed in 97.6% of pancreatic cancers." (PMID 26919100, 2016).
pancreatic cancer (continued). "To assess the physiological relevance of our in vivo observations, we examined the expression patterns of IGF-1R, EP2/EP4, MAP4K3, and PKC-θ in surgical specimens from pancreatic cancers based on immunohistochemical analyses." (PMID 25638159, 2015). "Combinations of anti-IGF-1R antibodies or small molecule inhibitors of IGF-1R with gemcitabine, which are used widely to treat pancreatic cancer, have additive or synergistic effects on growth and survival." (PMID 25638159, 2015). "Upregulation of miR-497 suppressed the malignancy of pancreatic cancer and re-sensitized PDAC cells to gemcitabine by directly downregulating IGF-1R protein expression." (PMID 24667580, 2014). "Several growth factor receptors such as insulin–like growth factor 1 receptor (IGF-1R), epidermal growth factor receptor (EGFR), etc., are aberrantly expressed in many types of cancer including pancreatic cancer." (PMID 24809702, 2014). "Silencing IGF-1R resulted in an anti-proliferative effect in PANC-1 and HPAC pancreatic cancer cell lines." (PMID 24809702, 2014). "For that, we evaluated the effects of IGF-1R inhibition using small interfering RNA (siRNAs) on tumor growth and metastasis in HPAC and PANC-1 pancreatic cancer cell lines." (PMID 24809702, 2014). "The present study aimed to elucidate the clinicopathologic role of insulin-like growth factor-1 receptor (IGF1R) and IGF binding protein-3 (IGFBP3) in patients with pancreatic cancer." (PMID 23962053, 2013). "The present study suggests that combined evaluation of IGF1R expression and IGFBP3 expression is a useful prognostic factor in pancreatic cancer, especially with clinical stage II tumors." (PMID 23962053, 2013). "In this study, IGF1R and IGFBP3 expression was examined, and their potential roles as prognostic markers in patients with pancreatic cancer were evaluated." (PMID 23962053, 2013). "Both high IGF1R expression and low IGFBP3 expression represent useful prognostic markers for patients with curatively resected pancreatic cancer." (PMID 23962053, 2013). "Decreased IGF-1R expression enhanced ARR apoptosis induction and inhibited pancreatic carcinoma growth and sphere formation." (PMID 22570653, 2012). "At least in pancreatic cancer, it has been shown that dual inhibition of FAK and IGF-1R led to a synergistic decrease in cell proliferation and increase in cell detachment and apoptosis compared with inhibition of either pathway alone." (PMID 21849056, 2011). "Insulin-like growth factor 1 receptor (IGF1R) targeted antibodies and tyrosine kinase inhibitors are being investigated in a variety of tumor types including pancreatic cancer." (PMID 20331897, 2010). "Recent mechanistic combinatorial targeted therapy approaches, such as double inhibition of IGF1R and ERK signaling in organoid models, display increased sensitivity of pancreatic tumors to autophagy inhibitors such as hydroxychloroquine and serve as a precedence to our concept." (PMID 39000545, 2024). "Clinical trials, exemplified by the phase III trial investigating ganitumab, an antibody targeting IGF1R in conjunction with gemcitabine for metastatic pancreatic cancer patients, failed to yield a statistically significant improvement in survival." (PMID 39087024, 2024). "inhibited the PI3K/Akt signaling pathway by knocking down the IGF-1R gene, thereby inhibiting the proliferation of pancreatic cancer cells and increasing the sensitivity of anticancer drugs, which to some extent proves the role of IGF-1 in pancreatic cancer." (PMID 36755926, 2023). "For example, SNHG12 participates in regulating IGF1R-induced proliferation and metastasis of osteosarcoma cells by modulating miR-195-5p; BANCR regulates Wnt/β-Catenin signaling pathway by sponging miR-195-5p, thereupon promoting pancreatic cancer progression." (PMID 35037833, 2022). "Observed significant association between pancreatic cancer risk and polymorphisms in IGF1, IGF1R & IGFBP1 but SNPs in IGFBP5 were not significant." (PMID 36465383, 2022).
pancreatic cancer (continued). "FBLN2, FBLN3, and FBLN5 have been shown to regulate Notch, Insulin Growth Factor receptor (IGF1R), EGFR signaling pathways, respectively, in glioma, lung, and pancreatic cancers." (PMID 32719793, 2020). "Nonetheless, it is apparent that miR-29a modulates extracellular IGF-1/IGF-1R signaling in PSCs, and intracellular NRAS expression in pancreatic cancer cells, which indicates a functional role of the molecule in tumor-stromal crosstalk via insulin/IRF -RAS/MAPK signaling mechanism in PDAC." (PMID 32660466, 2020). "The assay also showed that KAN0439834 did not dephosphorylate EGFR and IGF-1R, kinases which are overexpressed in pancreatic carcinoma cells." (PMID 29856777, 2018). "Additionally, our lab demonstrated that suppressed IGF-1R protein expression via miR-497 up-regulation was able to re-sensitize pancreatic cancer cells to gemcitabine and that plasma IGF-1R can discriminate pancreatic cancer from other pancreatic tumors." (PMID 27344185, 2016). "According to these analyses, 17.4% of the cases were quadruple-positive for IGF-1R, EP2/EP4, MAP4K3, and PKC-θ, indicating that crosstalk may occur between these signaling pathways in human pancreatic cancers." (PMID 25638159, 2015). "The clinical value of plasma insulin-like growth factor 1 receptor (IGF-1R) in pancreatic cancers has not been investigated." (PMID 24667580, 2014). "Therefore, IGF-1R silencing induces PTEN expression and inhibits phosphorylation of AKT, PI3K, mTOR and p-70s6kinase in pancreatic cancer cells." (PMID 24809702, 2014). "Here we clearly demonstrate that blocking IGF-1R expression enhances apoptosis and suppresses cell invasion, migration and metastasis via modulation of PI3K/AKT, MAPK and JAK/STAT signaling pathways in pancreatic cancer cells." (PMID 24809702, 2014). "Plasma IGF-1R displayed a potential value for distinguishing pancreatic lesions and could be a new biomarker for guiding TNM stage of pancreatic cancer." (PMID 24667580, 2014). "IGF-1R and IGF-1 are overexpressed in human pancreatic tumors." (PMID 22570653, 2012). "Similarly, a Phase II trial of cixutumumab (an IGF-1R mAb antagonist) combined with erlotinib and gemcitabine for stage IV pancreatic cancer also failed to extend progression-free survival." (PMID 41509070, 2025). "However, the potential benefit of using IGF-1R targeted therapy in pancreatic cancer is not fully explored." (PMID 24809702, 2014). "On the other hand, it has also been shown that the activation of IGF-1/IGF-1R and SCF/KIT axes in pancreatic cancer cells may contribute to the induction of HIF-1α through the stimulation of PI3K/Akt and/or Ras/MEK/ERK pathways and tumour angiogenesis under normoxic conditions." (PMID 23301832, 2013). "However the role of IGF-1R signaling is not yet well studied in pancreatic cancer cells." (PMID 24809702, 2014). "However, plasma IGF-1R levels in pancreatic cancer patients have not been detected." (PMID 24667580, 2014). "For instance, in pancreatic cancer therapy, a Phase III clinical trial (NCT01231347) of Ganitumab—a monoclonal antibody inhibiting IGF-1R activity—combined with gemcitabine failed to improve patient survival rates." (PMID 41509070, 2025).